CD38 (CD38 molecule)
Diseases named in the same sentence as CD38 in open-access papers (continued):
Sharing a sentence is not in itself a finding about the gene and the disease.
tumor (continued). "However, a follow-up study highlighted that NK cell depletion in response to daratumumab treatment does not correlate with patient response, so more research is warranted in order to determine whether CD38+ NK cells are truly required for tumor elimination." (PMID 31878283, 2019). "However, in addition to catalyzing the production of adenosine, CD38 may also promote tumor progression by inducing other tumor-supporting processes in the TME." (PMID 31861847, 2019). "Additionally, anti-CD38 antibody treatment experiments revealed that the expression of CD38 on MDSCs is functional in promoting tumor growth, as implantation of MDSCs crosslinked with an anti-CD38 antibody significantly repressed tumor growth compared to CD38high MDSC implantation." (PMID 31878283, 2019). "CD38 expression on tumor cells may predict clinical response to daratumumab therapy." (PMID 31783629, 2019). "Besides T cells and NK cells, CD38 is also expressed on dendritic cells and can induce a Th1 response, again highlighting a potentially anti-tumor immune population that may be inhibited with CD38 targeting and complicate treatment efficacy." (PMID 31878283, 2019). "However, if the affinity of the CAR is not carefully optimized, high affinity CD38-CARs, like many others, can readily cause on-target, off-tumor side effects." (PMID 29847570, 2018). "The anti-tumor response has not always been satisfactory, although a novel vaccination procedure has recently been developed in rabbits to stimulate the generation of IgG Abs that cause strong C-mediated lysis of myeloma cells carrying the CD38 antigen." (PMID 30319647, 2018). "In addition, daratumumab-mediated reduction of CD38 on MM cells may also result in reduced generation of immunosuppressive adenosine molecules, and thereby an improved host-anti-tumor immune response." (PMID 30294326, 2018). "Thus, the inhibition of the enzymatic activity of intracellular CD38 may have adverse effects on tumor proliferation." (PMID 30631755, 2018). "By suppressing effector T cell responses, CD38 may thereby promote tumor growth." (PMID 30524421, 2018). "Thus, ADO accumulates in the TME predominantly through the catabolism of extracellular ATP to ADO by CD73, CD39, and CD38 expressed on tumor and immune cells, and has been reported to mediate suppression of anti-tumor immunity through activation of ADO receptors." (PMID 30513816, 2018). "Daratumumab also demonstrated potent antitumor activity in CD38-expressing xenografts in immune deficient mice, suggesting that daratumumab may mediate non-immune mediated anti-tumor activities in vivo." (PMID 31548533, 2017). "Thus, nanobodies that modulate the enzymatic activity of CD38 could have a therapeutic application for counteracting the immunosuppressive and tumor promoting activities of CD38." (PMID 29084989, 2017). "Thus, the mechanism of anti-CD38 novel agent may suggest that they possess an outstanding effect on tumor cells than other traditional regimens in triplet regimens for RRMM and single regimen for heavily pretreated MM patients." (PMID 28454113, 2017). "Therefore, targeting of CD38 by miR-708-5p would suggest a tumor suppressive role in CLL." (PMID 29050362, 2017). "Besides the high specificity and affinity to CD38, the efficient imaging of CD38+ tumors can be attributed to the small size of the nanobody which allows excellent tissue and tumor penetration and fast clearance of excess unbound nanobodies from the circulation by renal excretion." (PMID 29084989, 2017). "Within the tumours of treated animals, CTLA-4 blockade gave rise to a significantly altered expression of markers associated with dysfunction (PD-1, Lag-3 and CD160), activation (CD25, GITR and CD38), as well as co-stimulation and development (CD27 and CD127) on mLama4-specific T cells." (PMID 28916749, 2017).
tumor (continued). "Also modulation of determinants of sensitivity of the tumor cell toward CD38‐targeting antibodies with novel therapeutic approaches may lead to more effective regimens with increased quality of response and improvement in survival." (PMID 26864107, 2016). "In addition to CDC, the binding of daratumumab to CD38 on the surface of tumor cells has been shown to induce antibody‐dependent cellular cytotoxicity (ADCC), antibody‐dependent cellular phagocytosis (ADCP), tumor cell apoptosis, and modulation of the enzymatic activity CD38." (PMID 26864107, 2016). "Our data shows that this CD38-targeted, attenuated IFNα immunocytokine, dubbed “CD38-AttenukineTM”, is orders of magnitude less potent at stimulating antigen-negative cells than native IFNα, and yet maintains potent anti-tumor activity on antigen-positive cells." (PMID 27611189, 2016). "We next investigated whether the tumor-induced [Ca2+]i increase was dependent on CD38." (PMID 25879940, 2015). "Therefore, we further examined whether mouse Cd38+/+ NK cells and Cd38−/− NK cells differed in their ability to induce tumor cell adhesion when co-cultured with B16F10 cells." (PMID 25879940, 2015). "We next investigated whether tumor cell-induced NK cell granule polarization was affected by CD38 by analyzing the translocation of cytolytic granules containing perforin and granzyme B. In the absence of target cells, perforin and granzyme B displayed dispersed granules in NK cells." (PMID 25879940, 2015). "Because 8-Br-ADPR, an antagonistic analog of ADPR, inhibited the degranulation and cytolytic activity of NK cells, we investigated whether ADPR was endogenously produced in tumor cell-stimulated NK cells and if CD38 was the enzyme responsible for ADPR production." (PMID 25879940, 2015). "The presence of hemichannels in tumor cells even without CD38 expression might confer on them growth/migration advantages through increased autocrine/paracrine NAD+ signaling and the possible interaction with CD38 present in the membrane of adjacent non-tumor cells (e.g., stromal cells)." (PMID 25018732, 2014). "The availability of monoclonal CD38 antibodies and the rather restricted expression upon pathological neoangiogenesis in the human BCCs makes the CD38 receptor also an attractive immunotherapeutic target to prevent new vessel formation and thereby tumor growth." (PMID 23308177, 2013). "CellChat analysis revealed 89 ligand–receptor networks between HLA-DR+CD38+CD8+ T cells and malignant cells—24 originating from T cells and 65 originating from tumor cells." (PMID 41565617, 2026). "Diagnosis is primarily cytological, hinging on the classic “starry sky” appearance, alongside immunophenotyping that shows tumor cells positive for B‐cell markers (CD19, CD20, CD22, CD79a, CD38, PAX5) and germinal‐center markers (CD10, BCL6)." (PMID 40951226, 2025). "IHC staining revealed that the CD38‐EVs‐DoxMNs group exhibited the lowest Ki‐67 and PCNA expression compared to all other groups, indicating the most potent tumour proliferation inhibition." (PMID 40317915, 2025). "Reduced activity of CD38 increases the bioavailability of NAD and activates SIRT1, thereby regulating the growth and differentiation of T cells and tumor growth." (PMID 40529366, 2025). "The tumor cells in PBL express plasma cell markers, such as CD38 and CD138, and frequently lack the traditional B-cell markers, namely, CD20 and PAX5." (PMID 41497913, 2025). "The main areas of development concern trispecific antibodies that, by adding to the binding with the tumor antigen, introduce recruitment of effector cells, such as T cells via CD3, and co-stimulatory signal activation, for example, CD38 and CD28." (PMID 40003906, 2025). "Activation of lymphocytes, with the focus on subsets (CD8 T cells, NK cells and NKT cells) that are crucial in anti-tumor immune responses, was scored based on early-to-intermediate activation markers CD69, CD25, CD38." (PMID 40691137, 2025).
tumor (continued). "We also examined the expression of CD38, CD33, and CXCR2 in tumor tissues of TE10 tumor-bearing hu-HSC-NOG-EXL mice treated with AZD4547 10 mg/kg for 21 d and AZD4547 treatment significantly reduced the CD38, CD33, and CXCR2 levels in tumor tissues." (PMID 40722739, 2025). "Despite the reduced expression, CD38 activity increased, and NAD+ levels decreased, leading to diminished tumor cell growth, increased apoptosis, and senescence." (PMID 40529366, 2025). "Studies indicate that high CD38 expression correlates with an immunosuppressive TME, potentially facilitating tumor immune evasion by promoting the recruitment of regulatory T cells (Tregs) and myeloid‐derived suppressor cells (MDSCs)." (PMID 40677211, 2025). "CD38 participates in adenosine production by consuming NAD, and targeting CD38 restores sensitivity to ICIs and elicits a stronger IFN response in human tumor explants and organoid models." (PMID 41226585, 2025). "These antibodies exhibit higher affinity and binding activity for CD38 than for CD47, reducing potential on-target and off-tumor effects." (PMID 40013150, 2025). "Our findings reveal elevated CD38 expression in CTCL, making it a viable target for αCD38 antibody therapy to reduce tumor burden." (PMID 40057636, 2025). "CD38 is an ectoenzyme that converts NAD+ to adenosine, thereby leading to adenosine accumulation, which suppresses anti-tumor immunity." (PMID 40666944, 2025). "The capacity of CD38-specific BARs to induce complement-dependent cytotoxicity (CDC) was evaluated using Daudi luc, CA-46 luc, and LP-1 luc tumor cell lines as targets." (PMID 41254160, 2025). "Further experimental evidence has provided revealing a synergistic efficacy triggered by combined therapy of CD38 inhibitor with PD1 antibodies, significantly inhibited tumor growth, compared to that of their monotherapy." (PMID 40677211, 2025). "Several were most upregulated in specific subsets, such as multi-cytokine in CD8 memory; TIMD4/TIM3 in CD8 CM and γδT; CTLA4/CD38 in Treg, CD4 memory and CD8 CM; and OX40/EBI3 in tumor-infiltrating T cells." (PMID 40903640, 2025). "Studies above have demonstrated that MMW irradiation can down-regulate the levels of CD47, CD38, and TGF-β in the tumor microenvironment." (PMID 41383334, 2025). "To further identify A2AR-expressing cells in the tumor environment, we used eight-color multiplex immunostaining (A2AR, CD123, CD11c, CD3, CD19, MUM1, CD38 and PCK)." (PMID 41472728, 2025). "Other tumor ISGs regulated by type I IFNs such as NOS2 and CD38 can also have immune-suppressive effects and have been implicated to promote resistance to PD-1 pathway blockade." (PMID 39663510, 2025). "The lowest MFI were observed in CD34+/CD38+ cells and in H69 cells, which are a SSTR2-low expressing tumor model." (PMID 40521188, 2025). "We examined cytokine secretion profiles (IL-2, IL-4, IL-6, and IFNG) from activated T cells (CD69, IL-2RA, CD38, and HLA-DRB1) to evaluate T-cell activation in the CM tumor microenvironment, revealing consistently low expression levels." (PMID 40959090, 2025). "First, recent laboratory evidence suggests that the epigenetic silencing of CD38 in PCa cells enhances NAD availability, thereby conferring a survival advantage to tumor-initiating cells by improving mitochondrial function." (PMID 41001131, 2025). "VP301, a bispecific CD38 and ICAM-1 antibody, was designed to leverage the overexpression of these antigens on MM cells to enhance immune-mediated tumor destruction." (PMID 40597436, 2025). "The capacity of CD38-specific BARs to induce antibody-dependent cellular cytotoxicity (ADCC) was evaluated using Daudi luc, CA-46 luc, and LP-1 luc tumor cell lines as targets and hCD16-transduced NK92 cells as effectors." (PMID 41254160, 2025). "We found that tumor cell–conditioned medium suppressed RTX- and daratumumab-dependent cell-mediated cytotoxicity of NK cells against CD20+ Raji cells and CD38+ Daudi cells, respectively." (PMID 40163355, 2025).
tumor (continued). "The basic strategy is to obtain a reagent focusing its activity prevalently around the cells expressing CD38, which enables avidity-induced blocking of CD47 on the same cells, in this way avoiding unwanted off-tumor effects." (PMID 40013150, 2025). "The OE-KIF22 group mice had heavier weight and bigger volume of tumor, and IHC results suggested that KIF22, CDC25C, CD38, and Ki-67 were strongly stained in the OE-KIF22 group." (PMID 38713252, 2024). "Indeed, ISB 1442 induced killing of tumor cells in patient samples was superior to that of daratumumab and was significantly higher in samples from patients that relapsed from the anti-CD38 therapy; these observations suggest that ISB 1442 could be used as a salvage therapy." (PMID 38448430, 2024). "We compared ISB 1442 to clinically validated monospecific antibodies, anti-CD38 (daratumumab) and anti-CD47 (hu5F9, magrolimab) in several potency assays with tumor cell lines expressing varying levels of CD38 and CD47." (PMID 38448430, 2024). "Anti-PD1 treatment aims to reinvigorate exhausted tumor-specific CD8+ T cells and this (re-)activation apparently triggers a substantial increase in the proportion of CD38+ CD8+ T cells." (PMID 38680487, 2024). "The immunophenotype of tumor cells includes strong ALK expression (ALK gene rearrangement) and expression of plasma-cell markers CD38, CD138, and VS38C." (PMID 39906668, 2024). "ES is characterized by the uniform arrangement of small round bundles or diffuse tumor cells expressing CD99, FLI-1, Ki-67, CD38, and WT-1." (PMID 39139288, 2024). "To explore the relationship between the expression of CD38 and potential immunosuppression in SCLC, we evaluated the expression of CD38 and genes involved in anti-tumor immunity from two publicly available SCLC clinical datasets." (PMID 38533509, 2024). "In support of this notion, our integrated epigenetic and machine learning analyses, extracted from bone marrow–derived patient tumor samples, also support a critical role for STAT1 in governing surface CD38." (PMID 40453054, 2024). "However, this needs to be validated in vivo given that we also show that cycling 15% above anaerobic threshold profoundly increases CD3−CD56+CD38+ NK-cells in blood, and these cells may be susceptible to daratumumab-mediated ADCC via fratricide – a potentially deleterious off-tumour effect." (PMID 39411424, 2024). "Flow cytometric analysis 10 days after implantation confirmed the decrease in adenosine-synthesizing enzymes CD73, CD38, and CD203 in tumor cells from both KO lines, while CD39 protein was unchanged in Ptger4-KO and decreased in Ptges-KO tumors." (PMID 39298269, 2024). "ISB 2001 was designed to mediate strong binding to tumor cells expressing low levels of either TAA, through dual targeting of BCMA and CD38." (PMID 39261676, 2024). "CD38 is also abundantly expressed by most immune cells upon activation;50 therefore, the CD38-cGAMP interaction may play a regulatory role in immune cell-highly infiltrated tumor microenvironments, where cGAMP can be released by cancer cells spontaneously or upon treatment." (PMID 38746669, 2024). "CD38/CD47 BsAbs preferentially bound to CD38+/CD47+ Reh cells, indicating that compared to CD47 therapeutic Abs, BsAbs have lower potential for on-target, off-tumor effects in vivo." (PMID 38983860, 2024). "The trispecific antibody SAR442257 binds to CD38, CD3, and CD28 to enable both tumor targeting and TC activation." (PMID 38786100, 2024). "BsAbs had higher affinity and binding activity to the CD38 target than those to the CD47 target, decreasing the potential on-target potential and off-tumor effects." (PMID 38983860, 2024). "Multiple other tumor targets for TCEs, including GPRC5D, FcRH5, and CD38, are being pursued preclinically and clinically." (PMID 39364307, 2024).
tumor (continued). "In addition, we observed high heterogeneity of EMM cells, which could be further demonstrated on typical PC molecules; for example, the EMM cells of one patient virtually lost expression of CD38 and tumor cells from another patient had very low CD138 expression." (PMID 38493239, 2024). "Our findings showed that the CD38/CD47 BsAbs strongly blocked the CD47/SIRPα interaction in CD38/CD47 double-positive tumor cells, indicating that the inhibition of CD47/SIRPα depended on the engagement of CD38." (PMID 38983860, 2024). "Circulating CD8+CD38+ T cells, CD8+CD28+ T cells, and NK cells were identified as potential prognostic factors for tumor response and survival in patients with HCC." (PMID 38404585, 2024). "This is an important finding, as ongoing clinical trials are exploring combining novel agents that target CD38/CD39 with A2A or A2B adenosine receptor inhibitors to suppress adenosine production and improve tumor response." (PMID 38731962, 2024). "Previous studies have demonstrated variable expression of CD38 on NKTCL tumors, with high expression observed in approximately 50% of tumor samples." (PMID 38233570, 2024). "A panel of BsAbs targeting CD38 and CD47 developed based on the “mAb-tarp” platform showed potent tumor-killing ability in vitro and in vivo." (PMID 38983860, 2024). "While ISB 1442 induced a selective phagocytosis of only CD38+ MM cells, hu5F9 induced similar phagocytosis of both CD38+ and CD38-KO tumor cells, supporting the selectivity of ISB 1442 towards CD38-expressing tumor cells." (PMID 38448430, 2024). "Through tumor models, we confirmed that [68Ga]Ga‐AJ206 detects varying levels of CD38 expression and differentiates CD38 levels in bone lesions in disseminated disease models." (PMID 38421139, 2024). "Using a second-generation CD19 CAR paired with a CD38 CCR with dual-co-stimulatory domains, Katsarou demonstrated the improved targeting of ultra-low-density CD19 tumor cells (∼20 molecules/cell) that were resistant to second-generation CD19-CAR T cells." (PMID 39095991, 2024). "In a study of non-small-cell lung cancer (NSCLC), CD38+CD8+TRM was also observed within the TME and was shown to be crucial for anti-tumor immunity in NSCLC." (PMID 37377962, 2023). "The consideration of CD38 and NGAL-R as druggable co-targets for CLL immunotherapy is reinforced by the fact that both proteins are involved in tumor metabolism." (PMID 37760777, 2023). "Several studies as well as clinical trials have already shown the oncolytic potential of engineered measles virus retargeting the virus to tumor-specific ligands/antigens like CD20, CD38 or carcinoembryonic antigen (CEA)." (PMID 37310433, 2023). "Spatial distances of CD4+ T cells–CD38+ T cells, CD4+ T cells–neutrophils and CD38+ T cells–neutrophils prolonged and they were replaced by CD163+ macrophages in PT along with tumour progression." (PMID 37491740, 2023). "Then, CD38 siRNA was loaded to form CD38 siRNA@PLOV via ultrasound, which tends to target T cells and then downregulate CD38 expression at the tumor sites." (PMID 37896250, 2023). "Paraffin-embedded tumor samples were stained immunohistochemically for CD3, CD20, CD38, CD56, CD66b, CD117, and CD163 and XIAP." (PMID 36472768, 2023). "In the tumour context, we have demonstrated that NICD of P2X7R+ CD8 T cells following exposure to recombinant ART1 is exacerbated in the presence of CD38-blocking antibodies." (PMID 38022596, 2023). "A new “2‐in‐1” strategy is developed to insert CD38 chimeric antigen receptor (CAR) at the CD38 locus by CRISPR/Cas9, which can resolve fratricide and enhance tumor eradication." (PMID 37485647, 2023). "Thus, BCMA may be superior to CD38 in terms of on-target off-tumor effect theoretically." (PMID 36750969, 2023). "A multitude of tumor resistance mechanisms have been described in the literature that include resistance to ADCP, CDC, as well as impacts to CD38 expression and CD38 protein." (PMID 37840445, 2023).